PROM1 (prominin 1)
Diseases named in the same sentence as PROM1 in open-access papers (continued):
Sharing a sentence is not in itself a finding about the gene and the disease.
cancer (continued). "In particular, clusters 9, 10, 12, 13, 14, 16, 18, 19, 21, 26, 27, 28, 30, 34 and 35 not only expressed ductal cell markers (KRT19, MMP7, TSPAN8, SOX9 and LCN2), but also expressed cancer cell markers (MUC1 and PROM1)." (PMID 40362181, 2025). "In relation to its multiple roles and differential expression in normal tissues, stem cells and cancer cells, the transcriptional regulation of CD133 expression is complex with human PROM1 gene being driven by six promoters." (PMID 38532366, 2024). "Expression of ALDH1A1, ALPL, ITGA6, CD44, PROM1 (CD133), LGR5, and YAP1 upregulated in the E2 and E3 phenotypes was consistent with cancer hallmarks including cell plasticity, self-renewal, and drug-tolerant persistence." (PMID 38915538, 2024). "Further exploratory analyses revealed that CTLA4, PDCD1, and the cancer antigens MSLN, MUC1, EPCAM, and PROM1 presented significantly increase expression levels in the high-risk subtype group." (PMID 39712016, 2024). "Prominin 1 (PROM1, CD133) is a well-known marker of TICs in various carcinomas and is also a factor used to define the clinical severity of cancer by reflecting stem cell abundances in patients." (PMID 38409448, 2024). "Intriguingly, we also found that the cancer stem cells (CSC) score, calculated using common CSC markers (EPCAM, CD24, KRT19, SOX9, PROM1, CD44, THY1, CD47), was significantly higher in the EMT-subtype." (PMID 39095854, 2024). "Some cancer stem cell markers have shown a positive correlation with the degree of dysplasia, including CD44, retinal dehydrogenase 1, prominin-1, and podoplanin." (PMID 37893561, 2023). "PROM1, also known as CD133, is currently considered a valuable marker for stem cells and cancer stem cells (CSCs)." (PMID 37835379, 2023). "CD133 (Prominin 1, PROM1) is a transmembrane protein whose mRNA and glycosylated forms are highly expressed in a variety of human cancer cells." (PMID 36497465, 2022). "Gene expression analysis showed that epithelial cells in type 3 TETs expressed high levels of cancer stem cell (CSC)-related markers (NOTCH2, CD24, ALDH1B1 and PROM1)." (PMID 36115836, 2022). "The cytoplasmic C-terminal domain of PROM1 binds to PI3K and radixin, maintaining cancer stem cell properties and regulating glucagon-induced PKA activity, respectively." (PMID 36266314, 2022). "As demonstrated in the top DEGs, specifically cancer stem lineage clusters expressed high levels of stemness feature genes (MKI67, CD44, CD24, and PROM1) and key DEeRNAs (PHLDA1 and RASD1)." (PMID 36092920, 2022). "Intriguingly, the most prominent cancer stem cell marker, CD133/Prom1, was found to be a key regulator of ciliary dynamics and maintenance of the normal stem cell quiescence state." (PMID 34201019, 2021). "Analysis of cancer stem cells marker genes, CD44 and PROM1, by real time PCR showed their significant upregulation in both nandrolone or boldenone treated poPSCs, after 7 or 14 days of culture." (PMID 34769230, 2021). "The genes selected included epithelial (KRT5, CDH1, EpCAM), mensenchymal (VIM, SNAI1, TWIST), stem (ALDH1A1, PROM1), breast specific (ESR1, PALB2) and other genes related to cell cycle or other cancer pathways (CCND1, CTNNB1, Ki67, etc.)." (PMID 34071445, 2021). "Increased expression levels of LGR5, PROM1, KLF4, SOX2, and MYC in HGD and cancerous tissues support the malignant phenotype and the existence of cancer stem cells and demonstrate that they can be used to assess diagnosis and prognosis." (PMID 34452555, 2021). "We next screened the cell lines for cancer stem cell markers by staining for CD44, CD24 and prominin-1 (CD133)." (PMID 33924486, 2021). "CSCs were characterized by the expression of the stem cell markers TWIST, the epithelial cell adhesion molecule (EPCAM), the transcription factors SNAI1 (SNAIL) and SNAI2 (SLUG) and cancer markers such as CD44 and prominin-1 (CD133)." (PMID 34445612, 2021).
cancer (continued). "Several studies have shown that miR-1915-3p modulates multidrug resistance, anti-apoptosis and stem cell differentiation by targeting BCL2 apoptosis regulator (BCL2), prominin 1 (PROM1) and paired box 2 (PAX2) in multiple types of cancers." (PMID 34774019, 2021). "As demonstrated in the top DEGs, specifically cancer stem lineage clusters expressed high levels of stemness feature genes including ALDH1A1, PROM1, and NES, while ductal lineage cluster expressed high levels of ductal markers such as MMP7, TSPAN8, and SOX9." (PMID 34732701, 2021). "Compared with monolayer-culture GBM cell lines, cancer stem cell (CSC) markers such as SOX2, PROM1, POU5F1, MSI1, FUT4, and CXCR4 were upregulated in the spheroids." (PMID 34638384, 2021). "To verify that the spheres in our setup were enriched in cancer stem cells, we tested the expression of the stemness-related transcription factors POU5F1 (Oct4), SOX2, CD44, PROM1 (CD133), and NANOG in spheres and adherent cells 72 h after seeding." (PMID 34832951, 2021). "Expression of markers like CD44, CD133/prominin-1 or of classical pluripotency markers such as OCT4, SOX2 and NANOG are used to characterize stemness in cancer cells." (PMID 33544116, 2021). "To determine the utility of PROM1 and PROM2 as markers of cancer prognosis, we performed a systematic data analysis of numerous gene expression datasets with clearly defined distinguishing parameters between cancer and normal tissues." (PMID 31164716, 2020). "The clinical prognosis data were then used to prepare a multivariate survival plot to assess the effect of high/high, high/low, low/high, and low/low expression of PROM1 and PROM2 in each cancer." (PMID 31164716, 2020). "Although PROM1 has been studied as a CSC marker and a regulator of cancer progression and prognosis over the last two decades, specific studies regarding the relationship between PROM1 expression and prognosis in certain cancers are lacking." (PMID 31164716, 2020). "We observed that 2513, 1598, 3507, and 4206 genes positively correlated with PROM1 expression in esophageal (ESCA), pancreatic (PAAD), liver (LIHC), and prostate (PRAD) cancers, respectively." (PMID 31164716, 2020). "Based on the varying characteristics of prominins, we conclude that PROM1 and PROM2 expression differentially modulates the clinical outcomes of cancers." (PMID 31164716, 2020). "We also analyzed the interacting partners and genes co-expressed with PROM1 and PROM2 in various cancers and subsequently, analyzed these genes to predict the probable underlying signaling pathways involved." (PMID 31164716, 2020). "Next to in vitro propagation as spheres, cancer stem cell markers like prominin-1 (CD133) and CD44 antigen (CD44) are frequently used to identify cancer stem cells in CRC." (PMID 32927768, 2020). "CD133 (Prominin 1, PROM1) is a transmembrane protein whose mRNA and glycosylated forms are highly expressed in many human cancer cell types." (PMID 32460847, 2020). "The prognostic value of PROM1 and PROM2 expression levels for different cancer patients was also determined based on data from the PrognoScan database." (PMID 31164716, 2020). "To identify genes that correlate with PROM1 and PROM2 expression in selected cancers, we performed a systematic analysis using the R2 platform." (PMID 31164716, 2020). "Both Meta3 and Meta4 cells have high expression of many key markers of metaplasia, such as Wfdc2, Mal2, and Gpx2, and cancer stem cell (CSC) marker genes, such as Cd44, CD133 (Prom1), and CD166 (Alcam)." (PMID 31804471, 2019). "Cancer stem cells can be identified and isolated due to their specific markers, such as CD44, CD133 (prominin-1), CD117 (c-Kit), ALDH1 (aldehyde dehydrogenase), and OCT3/4 (POU5F1), the transcription factor of the POU (Pit-Oct-Unc) family." (PMID 31083587, 2019).
cancer (continued). "CD133 identified by the AC133 antigenic epitope, is the human homologue of murine Prominin-1, and is one of the most touted markers for the putative cancer stem cells in CRC." (PMID 30221090, 2018). "Particularly, 320-IWR cells overexpressed prominin 1 (CD133), a well-known marker of cancer stem cells, and mTOR activation was also reported in cancer stem cells." (PMID 28615517, 2017). "The general interest of prominin-1 has grown exponentially since this cell surface molecule, and particularly its AC133 epitope, marks cells harboring stem and cancer stem cell properties." (PMID 24911657, 2014). "As proposed for hematopoietic and neural stem cells, prominin-1 may have a specific role in intercellular communication via exosomes, and protein–lipid assemblies might be the essential structural determinant in the release process of prominin-1 by stem and cancer stem cells." (PMID 23767874, 2013). "To date, using sampling across limited types of tissues and cancers, five TATA-less promoters (P1–P5) have been identified in the 5′ upstream region of PROM1." (PMID 24194746, 2013). "Since identification of CD133/prominin-1, a pentaspan membrane protein, there is a huge body of literatures addressing characterizations of CD133+ and CD133− cells in normal and cancer cells." (PMID 23437259, 2013). "CD133, (PROM1) is a transmembrane protein that is widely used as a cell-surface marker for stem cell and cancer stem cell populations." (PMID 24194746, 2013). "Additionally, results for other drug sensitivity markers (ABCG2, ABCB1, BCL2; P < 0.00001) and cancer stem cells (CSCs) markers (ALDH1A1, PROM1; P < 0.01) were also presented." (PMID 40264043, 2025). "PROM1 (Cluster 4) links KRT19 suppression to cancer stem cell (CSC) dynamics." (PMID 40806403, 2025). "Previous studies have shown that CD276 upregulation promotes the expression of stem cell markers, such as Prominin 1 (PROM1/CD133), CD44, and POU Class 5 Homeobox 1 (POU5F1/Oct4), potentially facilitating the epithelial–mesenchymal transition (EMT) in certain cancers." (PMID 40136662, 2025). "For instance, the protein CD133/Prominin-1, expressed in haematopoietic stem cells, neural progenitor cells, and ependymal cells in the adult brain, is widely recognised as a CSC biomarker in various cancers, including those of the CNS, lung, and colon." (PMID 39316249, 2025). "This reduction correlated with increased expression of stem cell markers, such as PROM1, CK19, DLK1, SALL4, and EPCAM, suggesting that low SLC2A2 levels may promote cancer stem cell traits, malignancy, and therapeutic resistance." (PMID 40279337, 2025). "In addition, it was shown by promoter analysis that the expression of many cancer stem cell (CSC)-related genes such as TERT, BMI1, BSG (CD147), and PROM1 (CD133) was under the control of SP1, HIF1A, and MYC." (PMID 39590335, 2024). "Also known as, prominin-1, CD133 is a transmembrane glycoprotein involved in cell migration and cancer initiation." (PMID 38033871, 2023). "Moreover, class II tumors show elevated expression of KRT20, which is highly linked to differentiated umbrella cells or CIS lesions, and ALDH1A1, ADH1A2, PROM1 (CD133), NES, and THY1 (CD90), which are cancer stem cell markers." (PMID 37525073, 2023). "Previous studies have shown that PROM1 is a CSC marker and a regulator of cancer progression and prognosis, and its targeted drugs could hinder the progression of various cancers." (PMID 37563740, 2023). "Moreover, in the PTCSC3-overexpressing cell lines, Prominin 1 (PROM1) and ATP-binding cassette subfamily B member 1 (ABCB1) expression levels, two cancer stem-cell markers, were found to be diminished." (PMID 35804851, 2022). "EMT-like phenotypic transitions which transform differentiated cells to dedifferentiated cells with stem cell-like properties is related to increased expression of certain normal and cancer stem cell markers such as Slug, Twist, Sox2, CD44, Nanog, CD133 (PROM1), Oct4, and ABC membrane transporters." (PMID 36361653, 2022).
cancer (continued). "The detailed mechanisms need to be further investigated to understand the functions of Prom1 in neurons and nonneuronal cells, such as cancer stem cells." (PMID 33446881, 2021). "Multiple cell-surface proteins, e.g., CD133 (also known as PROM1), CD166, or CD44, have been proposed to identify distinct subsets of human colorectal CSCs, likely linking the TME with intracellular cancer-driver pathways." (PMID 33673710, 2021). "Furthermore, we identified genes that correlated with PROM1 and PROM2 in certain cancers, based on their levels of expression." (PMID 31164716, 2020). "Therefore, the R2 genomics platform was used to identify genes correlated with PROM1 and PROM2 in certain cancers in which these prominins are highly expressed." (PMID 31164716, 2020). "PROM1 and PROM2 were found to be differentially expressed in many cancer types." (PMID 31164716, 2020). "PROM1, LGALS1, CD44, FUT4 and HOXA10 were identified as hub genes, which were involved in focal adhesion, calcium-dependent phospholipid binding, connective tissue development and transcriptional misregulation in cancer." (PMID 32347296, 2020). "Thus, our multivariate survival analyses showed that the pattern of PROM1 and PROM2 co-expression modulated the clinical outcomes of patients with certain types of cancers, which may help our understanding of the underlying mechanism of cancer prognosis with respect to prominin expression." (PMID 31164716, 2020). "PROM1 and PROM2 were found to be differentially expressed in cancer and normal tissues." (PMID 31164716, 2020). "The co-expression (high/high), partial co-expression (low/high), and lack of co-expression (low/low) of PROM1/PROM2 were associated with skin, KIRC, and KIRP cancers, respectively." (PMID 31164716, 2020). "Ingenuity Pathway Analysis of the PROM1+ cell transcriptome, also revealed significantly regulated stemness and tumorigenesis pathways such as pluripotency, EMT, tissue factor in cancer, Ephrin receptor, HIPPO pathway, and ILK signaling, suggesting their potential involvement in liver tumorigenesis." (PMID 33173221, 2020). "Moreover, it was able to target cancer stemness and self-renewal ability by reducing (i) ALDH1 activity, (ii) the expression of stemness-related genes (PROM1, LGR5), and (iii) the colony formation ability." (PMID 30717428, 2019). "Additionally, cancer stem cell markers were also overexpressed in N1b PTMC (ALDH1A3: 4.9‐fold, TM4SF1: 7.6‐fold, and PROM1: 5.4‐fold) (all P < .001)." (PMID 31498560, 2019). "CD133, also named prominin-1, has been verified to be a CSC marker in many cancers." (PMID 28220856, 2017). "Of progenitor markers, we also observed a strong Prom1 expression in ACF and cancers by RNA ISH." (PMID 28747693, 2017). "CD133 is a five‐transmembrane cell surface glycoprotein family, and its gene, PROM1 is specifically located on chromosome 4p15, a region that contains genes related to mature organ homoeostasis, tumorigenesis, and cancer progression." (PMID 26471868, 2015). "Here, we found that prominin-1 was expressed in duct/cyst-like structures as well as in secretion of both non-neoplastic lesions and well or moderately differentiated malignant tumors, whereas it was lacking in high-grade poorly differentiated MEC." (PMID 24911657, 2014). "Less differentiated cancer tissues were negative for prominin-1 as observed particularly in high-grade MEC." (PMID 24911657, 2014). "Using transcriptional initiation events from a representative panel of 72 developmental, cancer, and normal CAGE libraries we have characterized PROM1 promoter utilization, confirming the activity of four out of five known promoters (P1–P4) and one novel alternate promoter (P6)." (PMID 24194746, 2013).
cancer (continued). "ACA (also known as CD133 or prominin-1) is a glycosylphosphatidylinositol (GPI)-anchored protein that is expressed on the surface of various stem and progenitor cells, including hematopoietic stem cells (HSCs), endothelial progenitor cells, neural stem cells, and cancer stem cells." (PMID 38256066, 2024). "In order to further characterize the effect of EIF4G2 protein depletion on cancer outcome, and to understand why EIF4G2KD cells are more resistant to therapies, we examined the prevalence of aggressive sub-populations within the control and EIF4G2KD cells by probing for CD133 (PROM1) and CD44." (PMID 38388710, 2024). "Also, 9-cis-retinoic acid suppressed cancer cells in CRC by increasing apoptosis and inhibiting COX-2 through the activation of PPARγ, while retinal suppressed CRC by inducing HOXA5 and repressing stem cell markers prominin 1 and ALDH1." (PMID 35178443, 2022). "This correlation analysis suggested that PROM1 and PROM2 perform different functions with respect to pathway regulation; however, they may have some similar functions in certain signaling pathways, in certain cancer types." (PMID 31164716, 2020). "Moreover, CD133 (PROM1) is a progenitor cell marker in liver and cancer stem cell marker in HCC." (PMID 32471201, 2020). "It remains to be clarified whether any relation between the non-polarized expression of prominin-1 by cancer cells and the pathological neovascularization exists." (PMID 24911657, 2014). "CD133 is the epitope of a glycosilated form of human prominin-1, which is a member of the pentaspan transmembrane glycoprotein, and expression of CD133 has been reported to be localized in normal neonatal and adult precursor cell as well as cancer initiating cells." (PMID 24586330, 2014). "Variability of PROM1 expression levels in human GBM and patient-derived xenografts (PDX) – from no expression to strong, uniform expression – highlights that PROM1 may not always be associated with or restricted to cancer stem cells." (PMID 25184684, 2014). "Interestingly, no prominin-1 immunoreactivity was detected in high-grade carcinomas." (PMID 24911657, 2014). "However, there is other evidence showing that Prom1-negative cancer cells also form tumors in vivo." (PMID 19718438, 2009). "Prominin-1 (CD133), a glycoprotein on stem and progenitor cells in normal tissues, is a proposed CSC marker in various cancers." (PMID 40136652, 2025). "Therefore, the discovery of prominin-1-a isoform from octopus ink as well as bioactive peptides (CCCRCCNRCGGRHMKY, IVLYFIGYSICVAIGILFIILIPLIGCCLCCCR, TYVTCLVILNTIILFAVVCTFITNELYK, SVAVPCSVLLLWILIAFSLVDHSFAQNSSQQHR) from this protein may open up new opportunities for cancer and stem cell studies." (PMID 37103345, 2023). "Isolation of CD133-positive cells enriches for a subset of cancer cells with higher proliferation rate and increased divergent differentiation, but the transcript level of PROM1 or the protein level of CD133 is not considered to be a defining marker of the stem cell state." (PMID 36333778, 2022). "Using PPI analysis, the critical pathway of functional genes was found involved in the hematopoietic cell lineage and transcriptional misregulation in cancer, including HOXA10, MEIS1, FLT3, CD14, PROM1, RUNX2, and RUNX1 (data not shown), indicating the dominant roles of HOXA and MEIS1 in MLL-R ALL." (PMID 36276286, 2022). "Also, mRNA expression of the cancer stem cell (CSC) markers CD90 (Thy1) and CD133 (Prom1) was not substantially different between wt and Casp2−/− liver tumors (Fig EV2C)." (PMID 33225610, 2020). "As numbers of studies found that cell stemness/differentiation may contribute to chemoresistance in cancers, negative correlations between PKM2 expression and stemness markers, including Sox2, CD24, and Prom1/CD133 mRNA levels, were detected in subjects from the TCGA-HNSC dataset." (PMID 38068962, 2023).
cancer (continued). "In addition, DENSpm-treated cells exhibited elevated levels of expression of several key stem cell markers including POU5F1, Sox9, CD44, BMI1, and Lin28B, although other transcripts that are found in liver stem and cancer stem cells remained absent (PROM1, CD133)." (PMID 30567412, 2018).